MTOR (mechanistic target of rapamycin kinase)
Diseases named in the same sentence as MTOR in open-access papers (continued):
Sharing a sentence is not in itself a finding about the gene and the disease.
ovarian carcinoma (647 papers, 2009 to 2026). A malignant neoplasm originating from the surface ovarian epithelium. "A recent study reported that HN1 is associated with mTOR in ovarian cancer cell lines, and its depletion via shRNA almost completely suppressed tumour formation in mouse xenograft models." (PMID 39805577, 2025). "The PI3K/Akt/mTOR oncogenic signaling pathway is implicated in epithelial ovarian cancer development (López-Reig and López-Guerrero, 2020)." (PMID 39967908, 2025). "It furthermore impaired SKOV-3 cells’ migratory capacity and affected mTOR (mechanistic target of rapamycin) signalling (via down-regulation of Rictor and Raptor, constituents of mTORC1/mTORC2 complexes), associated with ovarian cancer progression." (PMID 39335088, 2024). "An early study across multiple clinical trials in advanced breast, cervical, endometrial, and ovarian cancers showed a higher response to PI3K/mTOR inhibitors in patients with PIK3CA mutations versus patients without mutations." (PMID 39456616, 2024). "Targeting PI3K/AKT/mTOR can reduce stem cell-like properties in ovarian cancer cells, which are often associated with relapses and resistance to standard treatments." (PMID 39770406, 2024). "The concentration-dependent treatment of nitidine chloride causes autophagy by inhibiting the Akt/mTOR pathway in ovarian cancer." (PMID 39519229, 2024). "As will be further analyzed in this review, similar genetic alterations in mTOR pathway components occur in both eutopic and ectopic endometrium of endometriosis patients as well as in endometriosis-associated ovarian cancer." (PMID 37627318, 2023). "Response to mTOR inhibitor monotherapy was modest in recurrent ovarian cancers unselected for histology, mTOR mutational, and ER status, with response rates below 10% in two phase II trials." (PMID 37623437, 2023). "Due to its prominent role in cell cycle progression, derangement of mTOR signaling is implicated in a wide range of malignancies, including ovarian cancer, while it has also been proven to correlate with endometriosis." (PMID 37627318, 2023). "It is acknowledged that the alterations in genes associated with the PI3K/AKT/mTOR pathway are commonly found in ovarian cancer." (PMID 37221474, 2023). "For example, EGFR was associated with the mTOR pathway to mediate ferroptosis and apoptosis of ovarian cancer." (PMID 35359830, 2022). "This experiment showed that BJOE significantly increased autophagy and caused significant changes in related factors in mTOR signal pathway compared with ovarian cancer SKOV3." (PMID 35959437, 2022). "Because it is found to also be upregulated in ovarian carcinoma, and its deregulation has been associated with platinum-drug resistance, mTOR represents an attractive biological target for ovarian cancer therapy." (PMID 35582305, 2021). "The proliferation cell nuclear antigen (PCNA) clamp-associated factor PCLAF activates the PI3K/AKT/mTOR pathway in ovarian cancer cells." (PMID 34205406, 2021). "Resistin promoted the proliferation of ovarian cancer cells via the mTOR signaling pathway and was associated with phosphorylating P70S6K." (PMID 34659568, 2021). "All these findings indicated that AKT/mTOR signaling was implicated in the role of HVEM in hypoxic ovarian cancer." (PMID 32312328, 2020). "Other reports associate the dual inhibition of PI3K/mTOR with a strong impact on suppression of cell proliferation, induction of cell cycle arrest and apoptosis in ovarian cancer cells, and the sensitizing for treatments with paclitaxel or cisplatin." (PMID 33287446, 2020). "Activation of the PI3K/Akt/mTOR pathway in ovarian cancer has been associated with carcinogenesis and progression." (PMID 33659215, 2020). "This is likely due to their association with the RAS/RAF/MAPK and PI3K/PTEN/AKT/mTOR pathways, which are activated in 70% and 50% of ovarian cancer cases, respectively." (PMID 32754300, 2020).
ovarian carcinoma (continued). "Upregulation of mTOR activity is associated with prolonged acute injury in pulmonary epithelium and plays a role in the malignant transformation of ovarian cancer in humans." (PMID 32407290, 2020). "The PI3K/AKT/mTOR pathway is frequently dysregulated in ovarian cancer and is associated with poor prognosis." (PMID 32927828, 2020). "The mammalian target of rapamycin (mTOR) is closely associated with tumorigenesis and ovarian cancer development and its downregulation inhibits cancer cell proliferation and metastasis." (PMID 33234722, 2020). "Previous in vitro studies using ovarian cancer cell lines have associated mTOR inhibition with increased apoptosis." (PMID 31822716, 2019). "The mechanistic Target of Rapamycin (mTOR) has been linked with the pathogenesis of ovarian cancer, especially with its progression." (PMID 31338320, 2019). "Abnormal activation of PI3K/Akt/mTOR cascade is well documented in ovarian cancers, and it is associated with a more aggressive phenotype." (PMID 31052147, 2019). "IGF1/mTOR and Fas pathways, were also shown to be negatively enriched in platinum sensitive ovarian cancer patients with low risk score." (PMID 29910195, 2018). "We also found that the mTOR signaling pathway was uniquely mutated in drug‐resistant recurrent ovarian cancer and had a mutation rate of 60%." (PMID 29797793, 2018). "Elevated levels of sex steroids, activation of the insulin–IGF-1 axis, aberrant productions of adipokines and inflammatory cytokines have all been found to cause tumor growth through activation of the PI3K/AKT/mTOR pathway, including that of ovarian cancers." (PMID 26959121, 2016). "Overactive mTOR signalling is present in up to 80% of ovarian cancer samples and is associated with poor prognosis." (PMID 27036037, 2016). "Other molecular therapy is targeting the PI3K/AKT/mTOR pathway, which upregulation is associated with poor prognosis in ovarian cancer Its inhibition induces apoptosis of tumoural cells." (PMID 27594911, 2016). "PI3K/AKT/mTOR pathway activation is associated with higher invasive and migratory capacities in subpopulations of human ovarian cancer cell lines." (PMID 26267321, 2015). "PI3K/AKT/mTOR pathway activation was associated with enhanced invasive and migratory capacities in human ovarian cancer cell lines." (PMID 26267321, 2015). "Akt activity is frequently elevated in ovarian cancer and is closely associated with the upregulation of mTOR signaling." (PMID 24526917, 2014). "In a recent study, seven patients with advanced ovarian carcinomas harboring a PI3KCA mutation were enrolled onto clinical trials that included a PI3K/AKT/mTOR inhibitor." (PMID 24036443, 2013). "It is intriguing, in this respect, the finding that a hyper-active status of mTOR is associated with a poor prognosis in ovarian carcinoma patients." (PMID 22974323, 2012). "We hypothesize that the mTOR pathway plays a significant role in the development and progression of endometriosis-associated ovarian cancer (EAOC), and that it is dysregulated in this cohort of patients, potentially driving the transformation process." (PMID 38893278, 2024). "Similarly, MFG-E8 siRNA, another non-coding mRNA, has been implicated in the AKT/mTOR/S6K signalling pathway in ovarian cancer cells." (PMID 38893278, 2024). "In ovarian cancer patients, a hyperactive state of mTOR has been associated with a poor prognosis." (PMID 37526235, 2023). "In fact, cancer-associated alterations in the mTOR pathway may be found in normal uterine epithelium, likely acting as a first step towards ovarian cancer, through the intermediary stage of endometriosis." (PMID 37627318, 2023). "Mutations in the PI3K/AKT/mTOR pathway have been identified in ovarian cancers through TCGA." (PMID 36230617, 2022).
ovarian carcinoma (continued). "Interestingly, all these findings show that platinum resistance of ovarian cancer cells can be reversed by inhibiting mTOR (mTORC1/mTORC2), as specific mRNAs encoding survival, cell cycle, and other functions are inhibited." (PMID 35582305, 2021). "Given that the PI3K/AKT/mTOR signaling pathway is frequently mutated in ovarian cancer, we further examined whether the pathway was regulated by miR-582-3p." (PMID 34793263, 2021). "Moreover, high expression and mutation of the PI3K/AKT/mTOR pathways have shown to be a poor prognostic factor for patients with ovarian cancer." (PMID 33659215, 2020). "In addition, the elevated expression of GRP78 (HSP70) is implicated in 5-FU resistance of colorectal and ovarian cancer cells through modulation of PI3K/AKT/mTOR and c-Src/LSF/TS signaling axes, respectively." (PMID 31878360, 2019). "The mTOR signaling pathway was uniquely mutated in drug‐resistant recurrent ovarian cancer." (PMID 29797793, 2018). "To investigate whether miR-497 overexpression enhanced the cisplatin response sensitivity of ovarian cancer cells via targeting mTOR and p70S6K1, we performed mTOR and p70S6K1 loss- and gain-of-function experiments in ovarian cancer cells." (PMID 26238185, 2015). "Everolimus is a targeted drug that specifically inhibits the function of mammalian target of rapamycin (mTOR) pathway, which is dysfunctional in a subset of ovarian cancers and is associated with the up regulation of PTEN protein mutation and PI-3 K hyperactivation." (PMID 26141064, 2015). "Recent studies have implicated mTOR in several human diseases, including ovarian cancer." (PMID 23819061, 2013). "While there is no doubt that genetic alterations in PIK3CA, and AKT, or the loss of PTEN contribute to the role of the PI3K/AKT/mTOR pathway in the progression of ovarian cancer, this study suggests that that there are additional important factors that drive the PI3K pathway." (PMID 23591839, 2013). "Thus, L-leucine restriction in the diet may help treat ovarian cancer with BRCA1 mutation by less activating mTOR pathway." (PMID 38468344, 2024). "GALNT14 could inhibit mTOR activity to cause ferroptosis in ovarian cancer." (PMID 38583115, 2024). "The PI3K-AKT/mTOR pathway has a critical malignant transformation of human tumors and, specifically, is one of the major pathways that is aberrantly activated in ovarian cancer and associated with tumor progression and poor prognosis in patients with ovarian cancer." (PMID 33807612, 2021). "The combination of Curcumin and Resveratrol significantly impedes the PI3K/AKT/mTOR pathway, thereby sensitizing ovarian cancer cells exposed to Cisplatin." (PMID 40968783, 2026). "EGCG upregulates PTEN expression and downregulates PDK1, phospho-Akt, and phospho-mTOR, leading to inhibition of ovarian cancer cell proliferation and induction of apoptosis." (PMID 41608512, 2026). "The mechanistic target of rapamycin (mTOR) pathway is dysregulated in 55% of epithelial ovarian cancers, representing an appealing therapeutic target." (PMID 41827799, 2026). "In this study, we investigated the mTOR pathway in a clinical cohort of primary, chemo-naive, high-grade ovarian cancer samples, along with its regulatory post-transcriptional miRNA regulation." (PMID 41827799, 2026). "In ovarian cancer, METTL1-mediated tRNA m7G modification enhances the translation of AKT/mTOR pathway-associated proteins and promotes cell growth and metabolic reprogramming." (PMID 40895564, 2025). "In cancer-associated fibroblasts (CAFs), miR-1290 over-expression was correlated with changes in EMT markers and the promotion of mTOR and Akt phosphorylation within ovarian carcinoma cells, which ultimately increased tumor growth." (PMID 39859407, 2025). "The PI3K/AKT/mammalian target of rapamycin (mTOR) signaling pathway represents a therapeutic target for hormone-related diseases, including breast and ovarian cancer." (PMID 41227351, 2025).
ovarian carcinoma (continued). "Regarding the role of resistin on ovarian cancer cells, it enhances the proliferation of ovarian cancer cells by triggering the mammalian target of rapamycin kinase (mTOR) pathway and upregulating 70 kDa S6 kinase responsible for autophagy inhibition." (PMID 40076482, 2025). "Common signaling pathways associated with ovarian cancer include the MAPK, NF-κB, PI3K/Akt, and Akt/mTOR pathways." (PMID 40008006, 2025). "The PI3K/AKT/mTOR signaling axis is frequently overactivated in ovarian cancer and plays a key role in promoting cell proliferation, survival and chemoresistance, with PTEN functioning as a key negative regulator of this pathway." (PMID 41472794, 2025). "The PI3K/AKT/mTOR signaling pathway is frequently hyperactivated in ovarian cancer, contributing to uncontrolled cell proliferation, survival, and resistance to therapy." (PMID 41472794, 2025). "In ovarian carcinoma and triple-negative breast cancer, glutaminolysis inhibition with CB-839 enhances sensitivity to mTOR inhibitors." (PMID 40943167, 2025). "Regarding the PI3K/AKT/mTOR pathway, which is typically overactivated in ovarian cancer, it represents a regulatory mechanism controlling the activity of pro- and anti-apoptotic Bcl-2 family proteins." (PMID 40535773, 2025). "Branched-chain amino acids (BCAAs), though less studied in ovarian cancer specifically, show preclinical evidence of pro-tumor signaling activation (e.g., mTOR)." (PMID 41148804, 2025). "The PI3K/AKT/mTOR signaling cascade has been widely shown to be crucial in the tumorigenesis, chemoresistance, and radioresistance of ovarian carcinoma through various aberrations within the pathway and alterations at multiple regulatory points." (PMID 40656893, 2025). "As expected, HF remarkably inhibited phosphorylation of mTOR and eIF2α in ovarian cancer CAF1 and CAF2 respectively, which in turn affected ATF4 expression in a time‐dependent manner." (PMID 40126173, 2025). "LARP1 also regulates mitochondrial oxidative phosphorylation in response to the PI3K/mTOR pathway, contributing to ovarian cancer cell survival." (PMID 40018039, 2025). "The dysregulation of the AMPK/mTOR system is frequent in neoplasias and the activation of mTOR frequently leads to the induction of glycolysis in cancers including ovarian cancer." (PMID 40175359, 2025). "These compounds influence key metabolic and signaling pathways, including PI3K/Akt/mTOR, NF-κB, and Wnt/β-catenin, suggesting their potential as adjuncts to conventional chemotherapy and their role in improving treatment outcomes in ovarian cancer management." (PMID 40868085, 2025). "Previous research reports have found that Momordica charantia extract can inhibit ovarian cancer cells by activating the AMPK/mTOR signaling pathway." (PMID 40804263, 2025). "CCL2 released by omental adipocytes facilitates the migration and omental metastasis of ovarian cancer through the activation of PI3K/AKT/mTOR followed by an increase in HIF-1α and vascular endothelial growth factor A (VEGF-A)." (PMID 40076892, 2025). "Several research studies have verified that the initiation of the PI3K/Akt/mTOR signaling cascade suppresses autophagy in ovarian cancer." (PMID 40641524, 2025). "A previous study has indicated that DAP induces cytoprotective autophagy in ovarian cancer by mediating AMPK/Akt/mTOR signaling, which partially supports our results." (PMID 40304008, 2025). "Taken together, these findings highlight the complex, multilayered regulation of PTEN by cannabinoids and support further investigation of cannabinoid-mediated modulation of PI3K/AKT/mTOR signaling in ovarian cancer." (PMID 41472794, 2025). "Collectively, these results indicate that HF inhibited COL1A1 expression through mTOR‐eIF2α‐ATF4 axis in ovarian cancer CAFs." (PMID 40126173, 2025). "Overall, our study confirmed the oncogenic role of ATP6V1B1 in ovarian cancer and revealed that ATP6V1B1 promotes ovarian cancer progression via the mTOR/autophagy axis." (PMID 38735913, 2025).
ovarian carcinoma (continued). "A growing number of studies have emphasized the central role of the PI3K/AKT/mTOR pathway in the progression of ovarian cancer and chemotherapy resistance." (PMID 41154754, 2025). "Out of all these pathways, the PI3K/AKT/mTOR pathway is the most altered pathway in ovarian cancer cases." (PMID 38584538, 2025). "The deubiquitination enzyme USP18 can also up-regulate ovarian cancer development in ovarian cancer by activating the AKT/mTOR signaling pathway through direct regulation of mTOR and AKT proteins." (PMID 39759114, 2025). "Recent findings reveal that SHCBP1 also suppresses autophagic cell death by activating the AKT/mTOR pathway in ovarian cancer." (PMID 41009347, 2025). "GSK458, a PI3K/mTOR inhibitor, decreases the mTOR expression and suppresses the tumorigenesis, metastasis, and growth of ovarian cancer cell lines." (PMID 39519229, 2024). "Specific components of the mTOR complex, such as domain-containing mTOR-interacting protein, are similarly expressed in endometriotic and ovarian carcinoma tissues, highlighting the role of the mTOR signalling in connecting endometriosis to tumourigenesis." (PMID 39579091, 2024). "We found that HDAC7 expression is associated with poor prognosis of ovarian cancer patients and induces cell proliferation and invasion by activating AKT/mTOR pathway." (PMID 39431349, 2024). "In conclusion, a miRNA/mRNA axis in ovarian cancer CAFs modulating the proliferative and invasive abilities of ovarian cancer cells, possibly via the Akt/mTOR pathway, was demonstrated." (PMID 38402185, 2024). "Recent studies have also demonstrated that METTL3-mediated m6A modification can activate the PI3K/AKT/mammalian target of rapamycin (mTOR) pathway in ovarian cancer (OC) and retinoblastoma (Rb)." (PMID 39295872, 2024). "The effect of one of the active substances ofCentella asiatica, namelyAsiatic acid (AA) on P13 kinase (P13K)/Akt/mTOR has also been investigated as a therapeutic target in ovarian cancer cells." (PMID 38812527, 2024). "In prior studies, Dusp1 has been shown to impact mTOR in ovarian cancer, and TFEB, in turn, has been shown to negatively bind and regulate the DUSP1 promotor in melanoma." (PMID 39718832, 2024). "The PI3K/mTOR pathway is often hyper-activated and complexly cross-regulated in ovarian cancer, suggesting that there has a more complex network in molecular signaling crosstalk." (PMID 38238825, 2024). "miR-1290 overexpression in CAFs significantly promoted ovarian cancer cell viability, DNA synthesis, and cell invasion; besides, miR-1290 overexpression in CAFs also changed EMT markers and promoted mTOR and Akt phosphorylation within ovarian carcinoma cells." (PMID 38402185, 2024). "For instance, FAM83D promotes cell invasion and chemo-resistance by regulating AKT/mTOR and TGFβ1-pSMAD2/3 signaling in lung and ovarian cancer." (PMID 38454442, 2024). "In this study, we used two ovarian cancer cell lines to investigate the mechanism of SGs formation under the dual PI3K/mTOR inhibitor treatment." (PMID 38238825, 2024). "Combination of WEE1 and mTOR dual inhibition demonstrated synergistic effects in both ovarian cancer cell lines and PDX models." (PMID 38231277, 2024). "Suppression of UBE2S expression enhances apoptosis and impedes cell cycle progression via restraining PI3K/AKT/mTOR signaling, thereby restraining ovarian cancer prognosis, migration, and proliferation." (PMID 38312603, 2024). "Although numerous clinical and preclinical trials have evaluated mTOR inhibitors in ovarian cancer, several challenges have hindered their progression into clinical practice." (PMID 38893278, 2024). "Resveratrol significantly inhibits the proliferation, migration, and invasion of A2780 and SKOV3 ovarian cancer cells through the AMPK/mTOR signaling pathway, while impairing glycolysis and inducing apoptosis in these cells." (PMID 38717641, 2024).